RNF217-AS1 (RNF217 antisense RNA 1)
Synonyms: STL
Gene: Long non-coding RNA gene on chromosome 6 (124,644,434 to 124,963,587, reverse strand). Ensembl gene ENSG00000236548.
Diseases named in the same sentence as RNF217-AS1 in open-access papers:
RNF217-AS1 is named in the same sentence as 1 disease in open-access papers, as found by Europe PMC text mining. Sharing a sentence is not in itself a finding about the gene and the disease.
RNF217-AS1 shares sentences with these, for which no sentence is quoted: infection (2 papers).